NOTCH3 (notch receptor 3)
Diseases named in the same sentence as NOTCH3 in open-access papers (continued):
Sharing a sentence is not in itself a finding about the gene and the disease.
Cognitive impairment (18 papers, 2017 to 2025). Abnormal cognition is characterized by deficits in thinking, reasoning, or remembering. "Compared with patients with classical CADASIL, patients with NOTCH3-preserved cysteine mutations had a significantly higher frequency of cognitive impairment and cerebral microhemorrhages, whereas anterior temporal pole and external capsule white matter high signal was rarely observed." (PMID 41018180, 2025). "Compared with CADASIL patients, cognitive impairment and cerebral microbleed frequencies were significantly higher in patients with NOTCH3 cysteine-sparing mutations, while the white matter hyperintensities in anterior temporal polar and external capsule were rarely observed." (PMID 39201482, 2024). "Interestingly, the proportion of cognitive impairment in patients with NOTCH3 cysteine-sparing mutations was significantly more prevalent (67.47% vs. 35.54%), similar to psychiatric disturbance (38.96% vs. 32.95%)." (PMID 39201482, 2024). "Insights from monogenic CSVD syndromes such as CADASIL (NOTCH3 mutations) and COL4A1/2-related angiopathies illuminate pure vascular pathways leading to cognitive impairment." (PMID 41153256, 2025). "NOTCH3 cysteine-sparing mutations in patients with clinical suspicion of CADASIL mainly manifested with gait and cognitive impairment but rare white matter hyperintensities in anterior temporal pole and external capsule." (PMID 39201482, 2024). "Third, because of a lack of magnetic resonance imaging, we failed to validate the relationship between white matter lesions and PD in NOTCH3-positive patients, which might play a role in the pathogenesis of cognitive impairment." (PMID 36570541, 2022). "Our findings showed that SVaD patients with NOTCH3 mutations had an earlier age of onset and a higher frequency of cognitive impairment in their family history than those without NOTCH3 mutations." (PMID 33942994, 2021). "The mean (SD) age at symptom onset for the 10 NOTCH3 mutation carriers was 80.5 (6.7) years, which was similar to that for the entire sample of ADSP EA cases (80.9 [9.1] years) and greater than age at onset of cognitive impairment among individuals with CADASIL (usually <50 years)." (PMID 30924900, 2019). "We conclude that cell intrinsic deficits in Notch3 signaling contributing to changes in adult hippocampal neurogenesis by changing the micromilieu is one vascular-independent mechanism in CADASIL patients, which might be a supporting factor for the development of cognitive deficits." (PMID 28345617, 2017).
Alzheimer disease (16 papers, 2017 to 2025). A progressive, neurodegenerative disease characterized by loss of function and death of nerve cells in several areas of the brain leading to loss of cognitive function such as memory and language. "According to this study, 90% of Notch3 mutations lead to CADASIL disease, 4% of Notch3 mutations lead to Alzheimer’s disease, and 4% of Notch3 mutations lead to white matter lesions." (PMID 38790158, 2024). "NOTCH3 mutations have also been associated with a number of neurodegenerative diseases such as; Alzheimer’s disease, Parkinson’s disease, multiple sclerosis, ALS and fronto-temporal lobar degeneration." (PMID 36107978, 2022). "Using amyloid positron emission tomography, the coexistence of Alzheimer’s disease pathology had already been reported in two patients among 15 patients with NOTCH3 variant." (PMID 33328970, 2020). "Besides, there may be a pathogenic link between NOTCH3 variants and Alzheimer's disease (AD)." (PMID 33942994, 2021). "While theoretically appealing, the peripheral sink hypothesis seems unlikely to operate for Aβ aggregates in Alzheimer's disease, but it will be interesting to learn whether it may be a contender to explain the reduction of Notch3 ECD aggregates following active immunization." (PMID 36524456, 2023).
lung adenocarcinoma (16 papers, 2013 to 2025). A carcinoma that arises from the lung and is characterized by the presence of malignant glandular epithelial cells. "Remarkably, Notch3 overexpression was also observed in KRAS-mutated lung adenocarcinoma cells and correlated positively with aldehyde dehydrogenase (ALDH) expression, resulting in enhanced CSC phenotype." (PMID 35463301, 2022). "The high expression levels of the NOTCH1 and NOTCH3 genes have been observed to be significantly associated with poor prognosis in lung adenocarcinoma." (PMID 28422717, 2017). "In addition, Notch3 was also associated with the overall survival rate of lung adenocarcinoma patients (pooled HR = 1.33, 95%CI: 1.07-1.67, p = 0.269 and I2 = 22.8%)." (PMID 25996086, 2015). "High levels of Jag1, DLL1, NOTCH1, and NOTCH2 mRNA were associated with better OS in lung adenocarcinoma patients, while Jag2, DLL3, and NOTCH3 mRNA correlated with poor survival." (PMID 40563292, 2025). "ELF3, playing an important oncogenic role in several tumors including PDAC, was reported to positively regulate Notch-3 gene transcription and modulate tumor-initiating cells in K-Ras-mediated lung adenocarcinoma." (PMID 37308977, 2023). "Because E74-like ETS transcription factor 3 (ELF3) was reported to bind to Notch-3 gene promoter with transcription regulation in K-RAS-mediated lung adenocarcinoma, we evaluated the interaction of KLF10 and ELF3 in Panc-1 cells." (PMID 37308977, 2023). "Our results showed a significant increase in the expression of Notch3 in lung adenocarcinoma cells treated with TANCS than that treated with medium, NeuCS, and TCCS respectively." (PMID 35118116, 2021). "Collectively, our study indicated that lung adenocarcinoma cells promote self-invasion and self-migration by activating neutrophils to upregulate the Notch3 expression of cancer cells." (PMID 35118116, 2021). "The results suggested that TANs promoted the migration and invasion of lung adenocarcinoma cells via Notch3." (PMID 35118116, 2021). "In this study, we investigated the prognostic role of CD66b + TANs in lung adenocarcinoma tissues and found a correlation between the density of TANs and the expression of Notch3." (PMID 35118116, 2021). "In lung adenocarcinoma, PKCλ-NOTCH3 signaling controls tumor-initiating cells (TICs), which exhibit such CSC-like properties as oncosphere formation and an asymmetric CD133 distribution during cell division." (PMID 32658903, 2020). "TCGA analysis showed that NOTCH3 was highly expressed in lung adenocarcinoma patients, which is consistent with previous studies." (PMID 29765324, 2018). "MethHC analyses demonstrated that the NOTCH3 methylation levels in human lung adenocarcinoma tissues were lower than that in human normal lung tissues." (PMID 29765324, 2018). "Western blotting analysis indicated that A549 cells, which are a lung adenocarcinoma cell line, stimulated the expression of NOTCH3 in NHDFs at a level that was similar to that induced by HO1-N-1." (PMID 27124156, 2016). "The results demonstrated that the expression of Notch3 protein in the lung adenocarcinoma group was higher than that of the normal paraneoplastic lung tissues." (PMID 23420695, 2013). "Additionally, the expression of Notch3 mRNA in the lung adenocarcinoma group was higher than that of the normal paraneoplastic lung tissues." (PMID 23420695, 2013). "Twenty years ago, the discovery that Notch could be first implicated as a catalyst for NSCLC pathogenesis was made when a translocation of a somatic chromosome t, resulting in overexpression of the Notch3 gene, was found in poorly differentiated and invasive lung adenocarcinoma." (PMID 35463301, 2022). "Therefore, whether Notch3 is involved in the migration and invasion of lung adenocarcinoma cells was explored." (PMID 35118116, 2021). "In lung adenocarcinoma tissues, the infiltration of TANS was positively correlated with the expression of Notch3 (p < 0.05)." (PMID 35118116, 2021).
lung adenocarcinoma (continued). "An earlier report suggests that PKCλ activates NOTCH3 expression via ELF3 phosphorylation, and this axis maintains the highly tumorigenic TIC phenotype in KRAS-mediated lung adenocarcinoma." (PMID 32658903, 2020). "However, after knocking down of Notch3, the migration and invasion of lung adenocarcinoma cells stimulated with TANCS were not enhanced." (PMID 35118116, 2021). "Likewise, lncRNA Small Nucleolar RNA Host Gene 11 (SNHG11) enhanced NOTCH3 expression sponging miR-193a-5p, thereby activating the NOTCH signaling pathway and facilitating the progression of lung adenocarcinoma." (PMID 40563292, 2025).
acute lymphoblastic leukemia (12 papers, 2013 to 2025). Leukemia with an acute onset, characterized by the presence of lymphoblasts in the bone marrow and the peripheral blood. "Further, in the pTCR-positive DN3 cells, a threshold level of NFATc1 activity is vital in facilitating T-cell differentiation and to prevent Notch3-induced T-acute lymphoblastic leukaemia." (PMID 27312418, 2016). "Besides, Pin1 activates the NOTCH3 signal by enhancing its cleavage and stabilizing its intracellular domain in T cell acute lymphoblastic leukemia (T-ALL) cell lines and mouse models." (PMID 30158600, 2018). "In addition to solid tumors, Notch3 is able to promote the survival of T acute lymphoblastic leukemia cells via regulation of MKP-1, which is a member of the MAPK pathway." (PMID 23426998, 2013). "The ability of Notch 3 to promote cancer cell survival has also been seen in hematological malignancies such as B-Acute Lymphoblastic Leukemia (B-ALL)." (PMID 33374160, 2020). "Using methylated CpG island amplification (MCA)/DNA promoter microarray, we identified Notch3 and Hes5 as hypermethylated in human B cell acute lymphoblastic leukemia (ALL)." (PMID 23637910, 2013). "It has also been suggested that nearly all human T cell acute lymphoblastic leukemia (T-ALL) overexpress Notch3." (PMID 23637910, 2013). "Additionally, HuD alters the Ikaros (IK) isoform profile by regulating alternative splicing of IK mRNAs in mouse thymocytes and human T–acute lymphoblastic leukemia (T–ALL) cell line Molt–3 cells in a Notch3–dependent manner." (PMID 33922479, 2021). "Not surprisingly, deregulated activation of Notch1 or Notch3 causes the development of “T-cell acute lymphoblastic leukemia (T-ALL)”, in both mice and humans." (PMID 32346377, 2020). "This may also be triggered by the pre-T-cell receptor (pre-TCR) whose functional cooperation with constitutive Notch3 expression is involved in the pathogenesis of a Notch3-induced T-cell acute lymphoblastic leukemia (T-ALL) characterized by a wide CD4+CD25+Treg expansion." (PMID 30364244, 2018). "In T acute lymphoblastic leukemia (T-ALL), an aggressive neoplasm of immature T-cells, Notch3 is commonly overexpressed but is not constitutively activated as Notch1 normally is." (PMID 33198378, 2020).
breast tumor (12 papers, 2013 to 2025). "NSD3 directly interacted with EZH2 and RNA polymerase II to stimulate H3K36 methylation-dependent transcriptional activation of NOTCH receptor cleavage-associated genes (including Adam12, DLL4, and Notch3), thereby activating Notch signaling to promote breast tumor progression." (PMID 34615858, 2021). "For this we used two cell types with endogenous NOTCH3, the human breast tumour cell line MCF7 and human VSMCs derived by differentiation of hESCs." (PMID 40764588, 2025). "We analyzed the genome sequencing and mRNA-sequencing data of specimens from the METABRIC study to define the linkage between NOTCH3 expression and overall survival of patients with claudin-low breast tumors." (PMID 30180881, 2018). "In particular, TNBCs show Notch3 amplification and overexpression, and Notch3 knockdown has been shown to reduce the proliferation of ErbB2-negative breast tumor cells." (PMID 29795369, 2018). "We could show that corresponding CTCs resemble those of primary breast tumors, but identified alterations also in pathways known to be important in brain metastasis formation including notch (gain of NOTCH3) and PI3K (gain of PDPK1) pathways." (PMID 31481116, 2019). "ERα+ breast tumor xenografts with a constitutive active Raf-1/MAPK signaling developed spontaneous lung metastases through the clonal expansion of cancer cells expressing a NOTCH3 reprogramming network." (PMID 30180881, 2018). "Additionally, Notch3 promotes proliferation and inhibits apoptosis of ErbB2-negative breast tumor cells via activation of the CSL (CBF-1/RBP-Jκ, Su(H) and Lag-1) pathway." (PMID 23426998, 2013). "We were then interested in the effects of Notch3 on genes from the PAM50 gene signature, which constitutes the basis of breast tumor molecular classifications, and observed that this signature was able to segregate tumors according to Notch3 status." (PMID 36854682, 2023). "Significantly, the role of aberrant NOTCH3 expression in promoting tumor self-renewal, invasiveness, and poor outcome was corroborated in unique TNBC cells from a patient-derived brain metastasis and in publicly available claudin-low breast tumor specimens." (PMID 30180881, 2018). "To further examine the role of ID4 in cancer stemness, we knocked down ID4 in MDA-MB-468 breast tumor cells using SMARTpool siRNAs, and tested the expression of a panel of stemness genes including Twist1, Twist2, Snail, Slug, BMP2, IRF1, SOX4, Foxk1 and Notch3." (PMID 36291790, 2022).
glioblastoma (12 papers, 2017 to 2025). The most malignant astrocytic tumor (WHO grade IV). "Immunohistochemistry revealed that ASAP3 and NOTCH3 were overexpressed in glioblastomas (GBMs)." (PMID 36382054, 2022). "We further validated the regulation role of METTL3 in DLL3, NOTCH3, and HES1 and identify its influence in cell proliferation of glioblastoma cell lines via cell experiments." (PMID 34589481, 2021). "This lncRNA interacts with the DHC10/NOTCH3/HES1-signaling pathway and plays a tumor-suppressive role in glioblastoma progression through inhibition of NOTCH3." (PMID 32283739, 2020). "This interaction between CHAC1 and Notch3 offers potential therapeutic insights, suggesting that targeting CHAC1 could amplify TMZ’s efficacy against glioblastoma by mitigating Notch3 activity (Chen P.-H." (PMID 39534397, 2024). "Similarly to VSMCs, also U87MG cells, a glioblastoma cell line that expresses low levels of PDE5, up-regulated both the A1 and A3 isoforms when transfected with NOTCH3, suggesting a common mechanism of NICD3 action on PDE5 expression in smooth muscle and neural cell types." (PMID 31434939, 2019).
osteosarcoma (12 papers, 2016 to 2025). A usually aggressive malignant bone-forming mesenchymal neoplasm, predominantly affecting adolescents and young adults. "On the other hand, EGCG could partially inactivate Notch3/DLL3 signaling cascade targeting SOX2OT variant 7 to reduce the stemness then abated drug-resistance of osteosarcoma cells." (PMID 29475441, 2018). "Increased expression of NOTCH1, NOTCH3, HES1 and HEY1 is also observed in pre- and post-treatment osteosarcoma patient samples with NOTCH3 expression associated with poorer 5-year survival." (PMID 40983796, 2025). "Analysis of 70 osteosarcoma specimens revealed that the high expression of NOTCH3 significantly correlated with a low survival rate of patients." (PMID 36975516, 2023). "In osteosarcoma, both in vivo and in vitro experiments indicate that the lncRNA SOX2OT variant seven can activate DLL3/Notch3 signaling, maintaining the stemness and doxorubicin-resistance of tumor cells." (PMID 34195229, 2021). "We therefore examined the effect of EZH2 silencing on the protein expressions of cancer stem cell markers; include CD44 and Notch-3 in osteosarcoma cells." (PMID 27223261, 2016). "A study found that NOTCH3 could also promote the invasion and metastasis of osteosarcoma cells by upregulating the downstream target genes Hes1 and MMP7." (PMID 36975516, 2023). "Furthermore, multivariate analysis revealed that NOTCH3 was an independent prognostic factor for osteosarcoma." (PMID 36975516, 2023). "Moreover, Jag2 and Notch4 are highly expressed in some murine osteosarcomas, and NOTCH3 has somatic copy-number alterations in about 10% of human osteosarcoma samples." (PMID 34439353, 2021). "Not long ago, Notch3 overexpression also was confirmed to be associated with metastasis and poor prognosis in osteosarcoma patients." (PMID 32665038, 2020). "On the other hand, EGCG could inactivate Notch3/DLL3 signaling targeting SOX2OT variant 7 to reduce the stemness of OS cells and then abated drug-resistance of osteosarcoma cells." (PMID 29475441, 2018). "Furthermore, stem cell markers of CD44 and Notch-3 were decreased in osteosarcoma cells after inhibition of EZH2." (PMID 27223261, 2016). "Treatment of osteosarcoma cells with epigallocatechin gallate, a polyphenol from green tea, can counteract the SOX2OT-7/DLL3/Notch3 axis, thus inhibiting cancer progression." (PMID 34195229, 2021). "However, the expression and clinical significance of NOTCH2 and NOTCH3 in osteosarcoma have not been reported." (PMID 36975516, 2023). "We have previously shown that the osteosarcoma cell line K7M2 actively expresses Notch genes (Notch1, Notch2, and Notch4; Hes1), but not Notch3." (PMID 27378829, 2016).
pulmonary hypertension (12 papers, 2012 to 2025). Increased pressure within the pulmonary circulation due to lung or heart disorder. "In an important study, Thistlethwaite and colleagues demonstrated that NOTCH3 was upregulated in patients with PAH and that Notch3−/− mice were resistant to developing pulmonary hypertension when exposed to low oxygen levels." (PMID 35472289, 2022).
triple-negative breast carcinoma (12 papers, 2015 to 2024). An invasive breast carcinoma which is negative for expression of estrogen receptor (ER), progesterone receptor (PR), and human epidermal growth factor receptor 2 (HER2). "NOTCH3 was reported to highly express in ER-positive and triple-negative breast cancer and contributed to prolonging OS." (PMID 38750402, 2024). "NOTCH3 expression contributes in the development of metastasis in both ERα positive and triple-negative breast cancer models." (PMID 34094972, 2021). "NOTCH3 and NOTCH2 mutations were detected in a subset of Chinese patients with triple-negative breast cancer." (PMID 33968723, 2021). "Breast tumours with high Notch3 levels are enriched in the triple-negative breast cancer (TNBC) subclass that lacks estrogen receptor, progesterone receptor (PR) and human epidermal growth factor receptor 2 (Her2) expression." (PMID 32210034, 2020). "The role of NOTCH3 expression in inducing a metastatic phenotype was corroborated in highly invasive MDA-MB-231 triple-negative breast cancer (TNBC) cells isolated from lung metastases." (PMID 30180881, 2018). "Consistently, Notch3 was found to be overexpressed in highly aggressive triple negative breast cancer samples and correlated with poor patient survival." (PMID 30042822, 2018). "Cellular function experiments were conducted to evaluate the role of NOTCH3/miR-223/ZEB1 in the proliferation and invasion of triple-negative breast cancer (TNBC)." (PMID 38164285, 2024).